PAX3 (paired box 3)
Diseases named in the same sentence as PAX3 in open-access papers (continued):
Sharing a sentence is not in itself a finding about the gene and the disease.
medulloblastoma (4 papers, 2010 to 2021). A malignant, invasive embryonal neoplasm arising from the cerebellum. "Nfe2l2 (Nuclear factor erythroid 2-related factor 2) and Pax3 (paired box gene 3) influence Srebf1 expression in mouse liver and human medulloblastoma cell line." (PMID 24806461, 2014). "PAX3 is known to be involved in tumors originated from neural crest and has been related to neural cell adhesion molecules polysialylation, and, subsequently, cell–cell and cell–substratum interactions in medulloblastoma cells." (PMID 32508873, 2020). "Additionally, these modules were interconnected via several hub genes, namely, FGFR1, BMP4, PAX6, PAX3, SOX9, and GLI2, all of which have been related to medulloblastomas in previous studies." (PMID 32508873, 2020).
cleft palate (3 papers, 2012 to 2018). Cleft palate is a fissure type embryopathy that affects the soft and hard palate to varying degrees. "Among these genes, ablation or mutation of Alx3, Lhx8, Pax3, Pitx1, Shox2, and Zeb2 induces cleft palates in humans and/or mice." (PMID 27329940, 2016). "Aberrant expression of Pax3 in the later stages of NCC development has been reported to manifest cleft palate and abnormal osteogenesis in mice." (PMID 30169530, 2018). "Studies in mice have demonstrated that failure to down regulate PAX3 during neural crest differentiation leads to cleft palate, due to inhibitory effects on osteogenesis." (PMID 23028347, 2012).
Hydrocephalus (3 papers, 2016 to 2022). Hydrocephalus is an active distension of the ventricular system of the brain resulting from inadequate passage of CSF from its point of production within the cerebral ventricles to its point of absorption into the systemic circulation. "Of clinical significance, we show that simultaneous heterozygous mutation of Pax7, a Pax3 paralog, induces hydrocephalus in compound heterozygous Pax3/Pax7 mice." (PMID 26949601, 2016). "Our study thus provides the first experimental data to understand the etiology of hydrocephalus in some patients with known PAX3 mutations." (PMID 26949601, 2016). "Moreover, via use of Pax3/Pax7 compound heterozygous mutations, we provide the first experimental mouse data to link the combinatorial mutation of Pax3 and Pax7 to occurrences of congenital hydrocephalus." (PMID 26949601, 2016). "Thus, the impact of Pax3 mutation upon hydrocephalus pathogenesis lies in the neuroepithelium which gives rise to the third ventricle and not the P0-Cre-marked NC lineages." (PMID 26949601, 2016). "Additionally, conditional Pax3 targeting using Pax7−Cre and P0-Cre, which separately mark only neuroepithelium or NC, respectively, enabled us to define the neuroepithelium as the primary site where the loss of Pax3 causes hydrocephalus." (PMID 26949601, 2016). "However, it remains to be determined whether maternal diabetes reduces Pax3 protein levels early enough during embryogenesis or whether reduction of Pax3 expression in diabetes-exposed mice embryos can cause hydrocephalus." (PMID 26949601, 2016). "While Pax7 systemic deletion does not cause NC-associated defects, it does exhibit overlapping expression, and Pax3-Pax7 compound heterozygous mice develop hydrocephalus, suggesting combinatorial function." (PMID 34355692, 2021). "Here we demonstrate that conditional deletion of the mouse Pax3 transcription factor results in fully-penetrant congenital obstructive hydrocephalus." (PMID 26949601, 2016). "As Pax3flox/flox/Pax7−Cre mutants exhibit hydrocephalus similar to Pax3flox/flox/Wnt1-Cre mutants, we examined Pax3 and Pax7 proteins." (PMID 26949601, 2016). "Favoring the theory that hydrocephalus is an outcome of multifactorial risks, only ~40% of compound Pax3+/Δ5/Pax7+/Δ2 mutants develop hydrocephalus." (PMID 26949601, 2016). "This Pax3 exon 5 allele does not result in any full length Pax3 expression, in which case, the congenital hydrocephalus phenotype is most likely due to lack of wild-type Pax3 within the dorsal neural tube." (PMID 26949601, 2016). "However, examination of coronal sections at P20 (n = 0/30) did not reveal any anomalies indicative of hydrocephalus, suggesting that overlapping and earlier expressed Pax3 can functionally compensate for loss of Pax7 during third ventricle development." (PMID 26949601, 2016). "Pathogenesis of Pax3+/Δ5/Pax7+/Δ2 mutant hydrocephalus is grossly and anatomically indistinguishable from that observed in Pax3flox/flox; Wnt1-Cre and Pax3flox/flox/Pax7−Cre mutants." (PMID 26949601, 2016).
prostate carcinoma (3 papers, 2015 to 2025). A carcinoma that arises from epithelial cells of the prostate gland. "Previous research has shown that silencing PAX3 can suppress tumor growth in several cancers, including gastric and prostate cancer, supporting its role as a potential oncogene." (PMID 41180518, 2025). "PAX3 is highly expressed in prostate cancer tissues and cell lines and promotes the progression of prostate cancer by inhibiting the TGF-β/SMAD signal axis." (PMID 34760693, 2021). "These represented cell cycle/mitosis; among others CCNE1, CCNE2, CCNG2, CCNL1, CCNT1, CDK12 and CDKN3, prostate cancer; including the androgen receptor (AR), metabolism as well as targets of the transcription factors E2F, AP2, SP1, ETF and Pax3." (PMID 26698305, 2015).
thyroid cancer (3 papers, 2016 to 2021). "Taken together, these observations suggest that epigenetic silencing is one of the major causes underlying PAX3 down-regulation in thyroid cancer." (PMID 27458157, 2016). "Given that metastasis is the major cause of death in thyroid cancer, we next evaluated the impact of PAX3 re-expression on thyroid cancer cell migration and invasion." (PMID 27458157, 2016). "The ectopic expression of PAX3 dramatically inhibited thyroid cancer progression in vitro and in vivo through inhibiting the activity of PI3K/Akt and MAPK signaling pathways and promoting the expression and activity of transcription factor FOXO3." (PMID 33817318, 2021). "Our data first demonstrated strong tumor suppressive activity of PAX3 in thyroid cancer through inhibiting cell growth and invasiveness." (PMID 27458157, 2016). "To better understand the mechanism of PAX3 as an oncosuppressor in thyroid cancer, we tested the effect of PAX3 re-expression on the PI3K/Akt and MAPK cascades in thyroid cancer cells." (PMID 27458157, 2016). "A series of in vitro and in vivo studies showed that ectopic expression of PAX3 dramatically inhibited cell growth and invasiveness in thyroid cancer cells through repressing the activities of PI3K/Akt and MAPK/Erk pathways and promoting FOXO3a activity." (PMID 27458157, 2016). "We found that ectopic expression of PAX3 strongly reduced phosphorylation of Akt and Erk, supporting that PAX3 exerts tumor suppressor function in thyroid cancer through modulating the activity of the PI3K/Akt and MAPK/Erk pathways." (PMID 27458157, 2016). "This was supported by our data that demethylation treatment significantly up-regulated PAX3 expression in thyroid cancer cells." (PMID 27458157, 2016). "Using quantitative RT-PCR (qRT-PCR) and Methylation-specific PCR (MSP) assays, we demonstrated that PAX3 was frequently down-regulated by promoter methylation in both primary thyroid cancer tissues and thyroid cancer cell lines." (PMID 27458157, 2016). "In summary, we demonstrate that PAX3 is a novel oncosuppressor, and is frequently inactivated by promoter methylation in thyroid cancer." (PMID 27458157, 2016). "Collectively, these results suggest that PAX3 regulates the expression and activity of FOXO3a through multiple mechanisms in thyroid cancer." (PMID 27458157, 2016). "Collectively, our findings unravel that PAX3 inhibits thyroid cancer cell metastasis through suppressing EMT process and the expression of metastasis-associated genes." (PMID 27458157, 2016). "Thus, we tested the role of PAX3 in thyroid cancer cells by a series of in vitro and in vivo experiments." (PMID 27458157, 2016). "To further clarify whether PAX3 is epigenetically silenced in thyroid cancer cells, we treated these cell lines with 5-Aza-dC or SAHA, respectively." (PMID 27458157, 2016). "In addition, our data showed that ectopic expression of PAX3 dramatically inhibited thyroid cancer cell proliferation, colony formation, migration and invasion, induced cell cycle arrest and apoptosis and retarded tumorigenic potential in nude mice." (PMID 27458157, 2016). "Accordingly, PAX3 was silenced in five of six thyroid cancer cell lines except for 8305C." (PMID 27458157, 2016). "In this study, we found that PAX3 was frequently down-regulated in PTC samples compared with control subjects, suggesting that PAX3 may be a potential oncosuppressor in thyroid cancer." (PMID 27458157, 2016). "In addition, we found that SAHA treatment restored PAX3 expression in these cells, indicating that histone deacetylation may also contribute to PAX3 inactivation in addition to promoter methylation in thyroid cancer cells." (PMID 27458157, 2016). "This was supported by our findings that ectopic expression of PAX3 markedly up- regulated FOXO3a downstream target genes, such as p21, p27, p130, Bim and TRAIL, and down-regulated another target gene cyclin D1 in thyroid cancer cells." (PMID 27458157, 2016).
thyroid cancer (continued). "Moreover, we demonstrated that ectopic expression of PAX3 in thyroid cancer cells strongly inhibited the expression of MMP-2, -9 and -14, suggesting that PAX3-induced metastasis suppression is also related with the activity of MMPs." (PMID 27458157, 2016). "Frequent inactivation of PAX3 in thyroid cancer cells and PTC samples but not in normal tissues indicates that PAX3 functions as an oncosuppressor in thyroid cancer." (PMID 27458157, 2016). "Thus, we can conclude that PAX3 inhibits the process of EMT by blocking the PI3K/Akt and MAPK/Erk cascades and enhancing expression and activity of FOXO3a in thyroid cancer cells." (PMID 27458157, 2016).
adenoid cystic carcinoma (2 papers, 2019 to 2024). A malignant tumor arising from the epithelial cells. "However, the PAX3-FOXO fusion was found in a 17-year-old patient with an adenoid cystic carcinoma of the trachea." (PMID 39338229, 2024).
brachydactyly (2 papers, 2024). A disease characterized by the presence of brachydactyly, including syndromic and non-syndromic forms. "Specifically, deletion of a TAD boundary between EPHA4 and PAX3 results in PAX3 adopting this cluster of limb enhancers, resulting in ectopic PAX3 expression and brachydactyly." (PMID 38436667, 2024).
Duchenne muscular dystrophy (2 papers, 2010 to 2023). Duchenne muscular dystrophy (DMD) is a neuromuscular disease characterized by rapidly progressive muscle weakness and wasting due to degeneration of skeletal, smooth and cardiac muscle. "We also tested the antineoplastic activity of piperacetazine in a second mouse model where PAX3::FOXO1 is expressed under a doxycycline-regulated promoter in an immortalized human Duchenne muscular dystrophy myoblast cell line (Dbt) expressing MYCN." (PMID 37732905, 2023).
lung carcinoma (2 papers, 2011 to 2021).
male pattern baldness (2 papers, 2019 to 2022). "Other PAX3 variants in lower LD with the lead SNP have also been associated with nasion position, monobrow, and male-pattern baldness." (PMID 35399580, 2022).
neural tube defect (2 papers, 2014 to 2018). A congenital defect characterized by failure of the neural tube to close completely; this results in the presence of openings in the brain or spinal cord. "It is known that embryonic AMPK activation stimulated by hyperglycemic and oxidative stress in GDM patients causes neural tube defect (NTD) through inhibiting the expression of pax3, an essential gene for neural tube closure." (PMID 30304773, 2018).
sensorineural hearing loss (2 papers, 2015 to 2022). "Unilateral sensorineural hearing loss (USNHL) is present in about 40% of deaf patients with PAX3 mutations (4/10)." (PMID 36329483, 2022).
viral infection (2 papers, 2012 to 2020). "While there was a significant amount of Pax3 and Pax7 protein expression at the beginning of culturing, Pax3 and Pax7 became gradually diminished upon Nkx3.2 and Sox9 viral infection, concurrently with the induction of cartilage genes, which should be consistent with a transdifferentiation process." (PMID 22768305, 2012). "The tissue specific activity of PAX3 can be bypassed, as demonstrated by the induction of MYOD1 in chick neural explants in which PAX3 is provided by RCAS based viral infection for 5 days." (PMID 33175861, 2020).
Autoimmunity (1 paper, 2020). The occurrence of an immune reaction against the organism's own cells or tissues. "PAX3 contributes to the embryonic development of the central nervous system and heart vasculature, which suggests that there are underlying associations between autoimmunity and the nervous system." (PMID 32721949, 2020).
Benign Kidney Neoplasm (1 paper, 2021). A non-metastasizing neoplasm that arises from the kidney. "Although there is no report about PAX3 in ccRCC, PAX3 gene is differentially hyper-methylated in chromophobe renal cell carcinomas compared with renal oncocytomas, a benign kidney neoplasm." (PMID 34760693, 2021).
breast tumor (1 paper, 2016). "All these results demonstrated that KDM3A/JMJD1A regulates breast tumor transformation through directly binding MYC and PAX3 oncogenes and modulating their transcription." (PMID 27034728, 2016).
cholesteatoma (1 paper, 2012). A pathologic process characterized by the proliferation of keratinizing squamous epithelium resulting in the accumulation of keratin and cells in the middle ear and/or mastoid. "PAX3 is down-regulated in cholesteatoma in both microarray and RT-PCR analysis." (PMID 23285167, 2012). "Moreover, tumor suppressor genes CDH18, 19 and ID4, which are known to be down-regulated in various tumors PAX3, LAMC2 and TRAF2B are also down-regulated in cholesteatoma." (PMID 23285167, 2012).
congenital sensorineural deafness (1 paper, 2024). "Type I, caused by mutations in the paired box 3 (PAX3) gene, manifests as dystopia canthorum, congenital sensorineural deafness, neural tube abnormalities, cleft palate, and localized depigmentation of the skin and hair on the lip." (PMID 39211634, 2024).
conjunctival melanoma (1 paper, 2025). "Intriguingly, data analysis revealed significant upregulation of PAX3 in conjunctival melanoma of poor (7.8 ± 2.3-fold, p = 0.01) and good prognosis (18.7 ± 5.5-fold, p = 0.01) compared to healthy conjunctival tissue." (PMID 40216818, 2025). "Immunohistochemical analysis revealed strong expression of PAX3 (green) in conjunctival melanoma compared to their respective healthy counterpart tissues." (PMID 40216818, 2025). "In conclusion, this study provides novel insights into the potential involvement of PAX3 in the development and progression of conjunctival melanoma." (PMID 40216818, 2025).
Currarino syndrome (1 paper, 2008). "Amino acid changes at this particular residue also have been shown to have a disease-causing effect in the case of the homeodomain transcription factors, HLXB9 (Currarino syndrome), LMX1B (Nail-patella syndrome), and PAX3 (Warrensburg syndrome)." (PMID 19052653, 2008).
endometriosis (1 paper, 2021). The growth of functional endometrial tissue in anatomic sites outside the uterine body. "There is PAX3 expression in cytotrophoblast cells and decidua cells during early pregnancy, so its disturbed expression might be involved in implantation defects in endometriosis." (PMID 34470627, 2021).
Exotropia (1 paper, 2022). A form of strabismus with one or both eyes deviated outward. "In summary, we present three separate cases of WS with congenital exotropia and find four novel variants in PAX3, COL11A2 and SOX10 genes." (PMID 36118891, 2022).
Facioscapulohumeral dystrophy (1 paper, 2025). Facioscapulohumeral muscular dystrophy (FSHD) is characterized by progressive muscle weakness with focal involvement of the facial, shoulder and limb muscles. "Further analyses including the functional analyses of DUX4, PAX3 and PAX7 in ECs could improve our understanding of a vascular pathogenesis in DUX4-related diseases, particularly in the contexts of cancer and facioscapulohumeral dystrophy." (PMID 40965075, 2025).
fibrosis (1 paper, 2021). the formation of excess fibrous connective tissue in an organ or tissue in a reparative or reactive process. "We speculated that Fus may exert its effect on cardiac fibrosis during AF via targeting Pax3." (PMID 33896391, 2021).
Floating-Harbor syndrome (1 paper, 2022). Floating-Harbor syndrome is a genetic developmental disorder characterized by facial dysmorphism, short stature with delayed bone age, and expressive language delay. "Examples of reclassification of VUS in our study include a novel and distinctive phenotype for the SRCAP gene, previously associated with Floating-Harbor syndrome only, a VUS in PRPS1 recently also reported by others, and small genotype-phenotype case series for LMBRD2 and PAX3." (PMID 35710456, 2022).
idiopathic scoliosis (1 paper, 2023). A scoliosis with no known cause. "Therefore, the PAX3 gene may cause non-synchronous migration of neural crest cells and different phenotypes of cells on both sides of the spine, resulting in idiopathic scoliosis." (PMID 38322243, 2023).
Infertility (1 paper, 2014). "PAX3 inhibition might considerably reduce concentrations of chemotherapeutic drugs, thereby decreasing therapy-related complications such as hearing loss, cardiac dysfunction and infertility." (PMID 24188742, 2014).
intestinal motility disorders (1 paper, 2024). "They found that mice with the presence of complex Pax3/Tcof1 exhibited a severe reduction in neural crest cell population and migration of neural crest cells to the colon, resulting in intestinal motility disorders in mice." (PMID 38444283, 2024).
malignant phyllodes tumor (1 paper, 2023). A phyllodes tumor with sarcomatous stroma. "PAX3 and SIX1 immunohistochemistry and gene expression have recently been identified in borderline and malignant phyllodes tumors and correlated with poor clinical outcomes." (PMID 37568749, 2023).
meningioma (1 paper, 2013). A generally slow growing tumor attached to the dura mater. "For the malignant meningiomas in our study, 26 genes were identified as significantly hypermethylated at promoter CpG islands, including eight genes involved in the biological pathway of neurogenesis (BARHL2, TLX3, FOXR1, HOXA11, HOXA6, HOXA9, OTX2 and PAX3)." (PMID 23349797, 2013).
microphthalmia (1 paper, 2021). Congenital or developmental anomaly in which the eyeballs are abnormally small. "Similarly, abolishing SUMO conjugation upregulates expression of MITF (Microphthalmia-associated transcription factor) MITF by enhancing SOX10 interaction with the cofactor paired box 3 (PAX3)." (PMID 34356679, 2021).
muscle cancer (1 paper, 2024). A malignant neoplasm affecting the skeletal or smooth muscles. "Interestingly, NCOA2 fusion with PAX3 has been shown to inhibit myogenic differentiation in muscle cancer." (PMID 39009887, 2024).
neuropathy (1 paper, 2016). A disorder affecting the nervous system that manifests with pain, tingling, numbness, and/or muscle weakness. "Importantly, the absence of expression of several embryonic genes in denervated SCs (AP2α, Etv5, Pax3) may provide a strategy to enhance or prolong the repair phenotype to improve recovery of function following PNS injury or neuropathy." (PMID 27058953, 2016).